MMP9 (matrix metallopeptidase 9)
Diseases named in the same sentence as MMP9 in open-access papers (continued):
Sharing a sentence is not in itself a finding about the gene and the disease.
colon carcinoma (continued). "We thus propose that MMP9 secretion by neutrophils infiltrating colon tumors will automatically lead to TGFβ activation and, consequently, T‐cell suppression if latent TGFβ is stored in the TME." (PMID 31793740, 2020). "Here, we investigated signaling pathways involved in ROS-driven CA-induced MMP-9 expression in human colon cancer cells." (PMID 32408577, 2020). "Integrin αvβ8 was found to not only increase the expression of MMP-9 but also promote its activity in colon cancer cells under the condition of latent TGF-β1." (PMID 32328185, 2020). "In this study, we showed that cholic acid (CA), a major primary bile acid, can induce MMP-9 expression in colon cancer HT29 and SW620 cells." (PMID 32408577, 2020). "Studies have revealed that MMP2 and MMP9 promote the degradation of the extracellular matrix, proliferation, and invasion of colon cancer cells." (PMID 32029709, 2020). "HOTAIR facilitates the migration and invasion of colon cancer cells in part via regulation of MMP-9." (PMID 33246471, 2020). "Consistently, the combined treatment of Aspirin and Cisplatin obviously attenuated the expression of main EMT-related proteins N-cadherin, β-catenin, Vimentin, MMP2, MMP9, Snail and Slug in human colon cancer cells." (PMID 31905343, 2020). "We show that mouse and human colon tumor neutrophils express high levels of MMP9 and that blocking MMP activity inhibits neutrophil‐mediated cleavage of latent TGFβ and T‐cell suppression." (PMID 31793740, 2020). "Collectively, these results suggest that CA can induce MMP-9 expression in human colon cancer cells." (PMID 32408577, 2020). "Andrographolide has previously been reported to inhibit NF-κB mediated upregulation of matrix metalloproteinase-9 (MMP9) in colon cancer cells." (PMID 32759728, 2020). "We analyzed the effects of integrin αvβ8-induced TGF-β1 activation on expression and activity of MMP-9 in colon cancer." (PMID 32328185, 2020). "A previous study indicated that MMP9 activity and expression were reduced by a CYSLTR1 antagonist (montelukast), and that M2 macrophages enriched in leukotriene D4 promoted the migration and invasion of colon cancer cells by inducing MMP9 expression." (PMID 33323552, 2020). "The expression of MMP-9 in whole-cell lysates of colon cancer cells was also determined by immunoblotting." (PMID 32328185, 2020). "We intended to analyse our patient population (Asian/Pakistani) and establish CAV-1 and MMP-9 significance in colon cancer." (PMID 31889941, 2019). "Colon cancer cells have been shown to be able to synthesize metalloproteinases, including MMP-9, a proteolytic enzyme capable of digesting type IV collagen - the main component of the basal membrane." (PMID 30760769, 2019). "This warrants further investigation to determine if CAV-1 and MMP-9 are biomarkers of early colon cancer or an indicator of abnormal growth in colon mucosa." (PMID 31889941, 2019). "We also observed that the expressions of common metastasis markers (MMP-2 and MMP-9) were significantly lower in miR-340 treated colon cancer cells than in control cells." (PMID 29435169, 2018). "This study can be seen as a validation of MMP-9 as a biomarker of colon cancer, even in frozen citrated plasma that has been in long-term storage." (PMID 29520667, 2018). "In contrast, CXCL1 and MMP9 are upregulated significantly in UEV1A-overexpressed HCT116 colon cancer cells." (PMID 29662619, 2018). "As expected, IL-6 enhanced the expression of MMP9, while metformin reduced the IL-6-enhanced expression of MMP9 in colon cancer cells." (PMID 30308035, 2018). "Supporting this anti-migratory activity of PKCδ, we found that Roy-Bz inhibited the migration of colon cancer cells in a PKCδ-dependent manner, with a reduction of MMP-9 and up-regulation of E-cadherin expression levels in colonospheres." (PMID 29348560, 2018).
colon carcinoma (continued). "Our in vitro model of human colonic carcinoma cell line HCT116 stably transfected with MMP9 displayed decreased proliferation compared to vector supporting the in vivo data of increased apoptosis." (PMID 27861153, 2017). "On the other hand some studies have shown that in breast and colon cancer, MMP9 expression has been correlated with both increased and decreased survival and distant metastasis." (PMID 27861153, 2017). "In concurrence with our results, it has been demonstrated that garlic-derived diallyl sulfide (DAS) disrupts MMP-9 expression in human colon cancer cells." (PMID 28187175, 2017). "OPN knockdown in a human colon carcinoma cell line by siRNA reduces vascular endothelial growth factor (VEGF), matrix metalloproteinase (MMP)-2, and MMP9, and suppresses colon cancer cell growth." (PMID 28505114, 2017). "DC-SIGNR, which was expressed in liver endothelial cells, increased the expressions of metallothioneins and MMP9 in colon cancer cells at 4 h with high activity." (PMID 28109307, 2017). "This evidence reveals that DC-SIGNR regulates the expression of metallothioneins by upregulating MMP9 during colon cancer liver metastasis." (PMID 28109307, 2017). "Previously, it has been shown that diallyl sulfide abolished the expression levels of MMP-9 in Colo205 human colon cancer cells." (PMID 28680385, 2017). "Heterologous expression of αvβ6 in a colon cancer cell line has been shown to be related, in part, to αvβ6-mediated MMP-9 secretion." (PMID 28634392, 2017). "Considering the fact that GI tract is mainly constituted of epithelial cells and colon cancer has epithelial origin, we have generated transgenic mice ‘Tg-villin-MMP9 (TgM9)’ that constitutively expresses MMP9 under villin promoter (TgM9)." (PMID 29212256, 2017). "Down-regulation of eIF4E suppresses the expression of VEGF, MMP-2 and MMP-9 simultaneously in colon cancer." (PMID 27907907, 2016). "We have previously found that integrinβ6 was able to induce the migration and invasion of colon cancer cells by up-regulation of MMP-3/MMP-9." (PMID 27835891, 2016). "Β6-siRNA encapsulated in TLPs was more likely to inhibit the activation of MMP-3 and MMP-9 than Lipo2000 and NTLPs (P < 0.01), which possibly resulted in the higher suppression of migration and invasion of colon cancer cells." (PMID 27835891, 2016). "This is a direct effect since 5-HT induces MMP-3 mRNA levels in human colon cancer Caco-2 cells and MMP-9 mRNA in human primary culture of leucocytes." (PMID 27478308, 2016). "More interestingly, inhibition of Fra-1 by miR-34a led to downregulation of MMP-1 and MMP-9 in colon cancer cells, and eventually inhibited cell migration and invasion." (PMID 26337460, 2015). "Stable overexpression of MMP-9 in a mouse colon carcinoma cell line resulted in increased angiostatin levels and decreased tumor growth and angiogenesis in vivo." (PMID 25233229, 2014). "By transfecting miR-34a into human colon cancer cells, the expression of both MMP-1 and MMP-9 was decreased substantially and ultimately led to inhibition of human colon cancer cell migration and invasion." (PMID 24518611, 2014). "We immunohistochemically investigated 68 specimens of colon cancer tissues and corresponding distal normal mucosa tissues using MMP-9 antibody." (PMID 24476461, 2014). "Within non-bone metastatic niches, increased circulating levels of gelatinase B/MMP-9 have been shown to enhance the frequency of colon cancer metastasis to lung in a mouse model." (PMID 24473089, 2014). "Increased CO2 concentration also elevated the mRNA expression of MMP-9 and invasive capability in colon cancer cell lines and human samples derived from a peritoneal metastasis." (PMID 24476461, 2014). "The difference of MMP-9 expression between colon cancer and distal normal mucosa was statistically significant (χ2 =64.602, P < 0.001)." (PMID 24476461, 2014).
colon carcinoma (continued). "Among the MMP family members, MMP-2 and MMP-9 are molecules crucial for cancer invasion, and are highly expressed in breast and colon cancer cells." (PMID 24520272, 2014). "The present study revealed that the LBF solution decreases the MMP-9 protein activity in colon cancer cells." (PMID 24765211, 2014). "This study analyzed the expression of MMP-9 in colon cancer patients and the relationship between this expression and clinicopathological features and survival." (PMID 24476461, 2014). "The reduced spreading effect and cell motility caused by miR-139-5p in colon cancer cells was revealed to be associated with the inhibition of the protein expression of cell migration and invasion molecules MMP7 and MMP9." (PMID 24885920, 2014). "Mice inoculated with colon cancer HCT-116 cells had high plasma levels of MMP-9 (mean ± SD : 125.6±14 ng/mL)." (PMID 24960186, 2014). "Collectively, these results suggest that CTHRC1 acts through ERK-mediated upregulation of MMP9 to promote increased invasiveness of colon cancer cells." (PMID 24504172, 2014). "Namely, activation of GC-C in colon cancer cells has been shown to reduce secretion of matrix metalloproteinase 9 (MMP-9) in a cGMP-dependent manner." (PMID 24577242, 2014). "DMP-1 is known to contribute to the invasion of colon cancer cells in a RGD-independent manner by bridging MMP-9 to CD44." (PMID 25396425, 2014). "In animal models and humans with inflammatory bowel disease, which is commonly associated with progression to colitis-associated colon cancer (CAC), MMP-9 is highly expressed in inflamed intestine." (PMID 24518611, 2014). "Ursolic acid (UA), a natural pentacyclic triterpenoid carboxylic acid distributed in medical herbs, also suppressed colon cancer cell migration by inhibiting MMP-9 expression." (PMID 24476461, 2014). "Positive MMP-9 expression was observed in 69.1% (47/68) of the colon cancer tissues, and in 4.4% (3/68) of the distal normal mucosal tissues." (PMID 24476461, 2014). "Smad4 binds to receptor-regulated SMADs, and suppresses colon cancer cell migration by regulating MMP-9 activity." (PMID 24518611, 2014). "CTHRCl-overexpressing colon cancer cell showed greater invasive capacity and higher levels of MMP9 expression than did control (mock-transfected) cells." (PMID 24504172, 2014). "We suggested that CCR1+ bone marrow (BM)-derived cells are recruited to the microenvironment of disseminated colon cancer cells, and produce metalloproteinases MMP9 and MMP2, helping metastatic colonization." (PMID 25326065, 2014). "The expression rate of MMP-9 in colon cancer tissues was significantly higher than that in distal normal mucosa (69.1% versus 2.9%, P < 0.001)." (PMID 24476461, 2014). "Our results showed that growth of liver metastasis from colon cancer was associated with elevated tumor tissues MMP-9, and treatment of ulinastatin significantly reduces MMP-9 expression." (PMID 23710449, 2013). "LEF1 knockdown reduced tumor cell viability, invasion capacity, and expression of MMP2 and MMP-9, but induced apoptosis in colon cancer cells." (PMID 24098538, 2013). "In conclusion, we showed that ulinastatin reduces recurrence after resection of colon cancer hepatic metastases in mice after hepatic surgery by inhibiting MMP-9 activation via the antifibrinolytic pathway." (PMID 23710449, 2013). "In summary, we demonstrated that UA inhibited cell proliferation and migration and induced apoptosis in colon cancer cells by simultaneously modulating the MMP9/CDH1, Akt/ERK, COX-2/PGE2, p300/NF-κB/CREB2, and cytochrome c/caspase-dependent signaling pathways." (PMID 23737956, 2013).
colon carcinoma (continued). "For example, TNF-α and IL-1β are potent stimulators for MMP9 in astrocytes, and IL-6 induces overexpression of MMP9 in human colon carcinoma cells, and TNF-α and IL-1β also can induce activation of NF-κB." (PMID 22529521, 2012). "We observed that 17β-estradiol treatment significantly inhibits PGE-induced activation of JNK1/2 within 30 min, and suppressed PGE2-induced expression of uPA and MMP-9 within 24 h in human LoVo colon cancer cells." (PMID 21859479, 2011). "The results suggested that PGE2 upregulates expression of uPA and MMP-9 via JNK1/2 signaling pathway in human LoVo colon cancer cells." (PMID 21859479, 2011). "For instance, an FPR variant receptor, FPRL1, in monocytic cells and a chemokine GPCR CXCR3 in colon cancer cells have also been shown to up-regulate MMP9." (PMID 20197768, 2010). "In malignant keratinocytes and colon cancer cells, increased expression of this integrin enhances MMP-9 secretion and MMP-9-mediated invasion." (PMID 19787098, 2008). "We show herein that inhibition of integrin αvβ6 expression in colon cancer cells suppresses MMP-9 secretion." (PMID 12177807, 2002). "We have previously reported a direct positive correlation between levels of expression of the β6-integrin subunit in SW480 colon cancer cells and MMP-9 secretion." (PMID 12177807, 2002). "Moreover, targeting MMP-9 to gene promoters in MMP-9 depleted colon cancer cells was shown to restore growth-related transcription, cell proliferation, and colony formation." (PMID 40381696, 2025). "Furthermore, elevated MMP-9 levels in colon cancer cells have been correlated with lymph node metastasis and Dukes’ stage." (PMID 40729026, 2025). "Also, cellular levels of MMP‐9 are very well correlated with extents of H3NT proteolysis in colon cancer cells in most cases." (PMID 38600695, 2024). "Similarly, the implantation of intestinal stents statistically significantly suppressed MMP-9 expression in the colon tumors of the CC mice (C-Control: p < 0.01; C-Cd: p < 0.05)." (PMID 38535948, 2024). "Given its vast (patho)physiological roles in both colon cancer and neuropathy, MMP9 seems to be a key factor that might drive the development of neuronal damage in colon cancer patients." (PMID 39664453, 2024). "Remarkably, artificial H3NT proteolysis at target gene promoters with dCAS9‐MMP‐9 is sufficient for establishing their transcriptional competence in colon cancer cells, underscoring the importance of MMP‐9‐dependent H3NT proteolysis per se in the transactivation process." (PMID 38600695, 2024). "Available studies reveal that MMP-2 and MMP-9 are involved in the aggressiveness of colon cancer." (PMID 39683504, 2024). "Although more work is required to clearly understand the molecular details, the results presented in this targeting study are sufficient to demonstrate the significance of MMP‐9‐dependent H3NT proteolysis in driving oncogenic gene expression in colon cancer cells." (PMID 38600695, 2024). "Our data establish new functions and mechanisms for MMP‐9 in driving the oncogenic transcription program in colon cancer through H3NT proteolysis, and demonstrate how this epigenetic pathway can be exploited as a potential therapeutic target for cancer treatment." (PMID 38600695, 2024). "Additionally, the treatment with punicalagin led to a suppression of MMP-2 and MMP-9 expression in colon cancer cells." (PMID 39858430, 2024).
colon carcinoma (continued). "Moreover, similarly blocking H3NT‐targeted MMP‐9 protease activity in xenograft models effectively attenuates the expression of target genes and impedes the growth of colonic tumor xenografts." (PMID 38600695, 2024). "The activated p38γ/c-Jun/MMP9 complex observed in human colon cancer tissues links these laboratory findings with clinical observations, illustrating that p38γ acts as both an activator and a cofactor of a transcription factor, which diversifies potential therapeutic approaches in CRC." (PMID 39664453, 2024). "Vast literature indicates that the increased levels of MMP9 in colon cancer (chapter 2 of this review) might be a driving factor in the development of CIPN (chapter 3)." (PMID 39664453, 2024). "In our study, the modulation of MMP-9 inhibitor protein is inhibited and downregulated via cell cycle control at G1 and S phase by epiqafzelechin, β-sitosterol and β-amyrin, thus can be used as an anticancer therapy for colon tumors." (PMID 38049552, 2023). "It was observed that TGFβ stimulation increased the levels of MnSOD, fibronectin, vimentin, MMP-9, and N-cadherin and decreased the levels of occludin and E-cadherin in colon cancer cells above the basal level, indicating the mesenchymal-phenotype of these cells is promoted by TGFβ." (PMID 35883447, 2022). "PCSK9 directly or indirectly upregulated Snail 1 and in turn to downregulate E-cadherin expression, but upregulate N-cadherin and MMP9 levels and thereafter, to induce colon cancer cell epithelial-mesenchymal transition (EMT) process and activated PI3K/AKT signaling." (PMID 36242053, 2022). "Besides, PCSK9 directly or indirectly activated Snail 1 and subsequently to downregulate E-cadherin (but upregulate N-cadherin and MMP9) and then induce the colon cancer cell EMT process." (PMID 36242053, 2022). "In addition to being highly digestible and nutritious, lupin and chickpea beverages showed specific bioactivities of MMP-9 inhibition, as well as a reduction in the migration of colon cancer cells." (PMID 35911116, 2022). "Furthermore, nuclear PKM2 was reported to regulate the production of TNF-α, IL-1β, MMP-2, and MMP-9 in colon cancer cells and to activate inflammasomes." (PMID 35256696, 2022). "Finally, the activity levels of both MMP2 and MMP9 were investigated by zymography in 26 colon cancer tissues and paired normal tissues, as well as in the corresponding sera." (PMID 34830271, 2021). "Moreover, a significant decrease in Caspase-3, which has been reported to regulate the metastasis of colon cancer cells, was observed, while MMP-9, which is also thought to be involved in EMT, was upregulated." (PMID 34502112, 2021). "Likewise, Zhou and Ma described a decrease of invasion and migration as well as decreased MMP-2 and MMP-9 mRNA in SW620 colon cancer cells treated with GA." (PMID 34680113, 2021). "GA has also been shown to activate AMPK in SW480 colon cancer cells and to decrease expression of invasion-associated proteins, including matrix metalloproteinase (MMP)-2, MMP-9, urinary-type plasminogen activator (uPa), and C-X-C chemokine receptor type 4 (CXCR4) in the SW480 cells." (PMID 34681204, 2021). "Finally, the activity levels of MMP2 and MMP9 in a cohort of colon cancer samples, including tissues and the corresponding sera, was also investigated by zymography." (PMID 34830271, 2021). "In our preliminary study, we detected serum VEGF, MMP-2, and MMP-9 in patients with colon cancer." (PMID 33747930, 2021). "In addition, PSVII@MCP-CaP significantly reduced the protein expressions of CD44, MMP-9 and N-cadherin in drug-resistant colon cancer tissue, while the expression of E-cadherin was increased." (PMID 34789268, 2021). "Moreover, PSVII@MCP-CaP significantly inhibited the invasion and migration of drug-resistant colon cancer cells by increasing E-cadherin protein expression and reducing N-cadherin and MMP-9 protein expression." (PMID 34789268, 2021).